IGLJ3 (immunoglobulin lambda joining 3)
Gene: Immunoglobulin joining (J) gene on chromosome 22 (22,904,850 to 22,905,025, forward strand). Ensembl gene ENSG00000211678.
Homologues: Paralogues in human: IGLJ2 (56% identical).
Diseases named in the same sentence as IGLJ3 in open-access papers:
IGLJ3 is named in the same sentence as 7 diseases in open-access papers, as found by Europe PMC text mining. Sharing a sentence is not in itself a finding about the gene and the disease. The quoted sentences say what the papers report.
periodontitis (3 papers, 2022 to 2025). An acute or chronic inflammatory process that affects the tissues that surround and support the teeth. "IGLJ3, DNASE1L3, ABCG1, DPEP2, and KIF19 are highly differentiated genes associated with diabetes and periodontitis." (PMID 38532421, 2024).
diabetes (1 paper, 2024). "IgLJ3 (Immunoglobulin Lambda Joining 3 is present in higher levels in people with type 1 diabetes than in people without diabetes." (PMID 38532421, 2024).
hematologic malignancies (1 paper, 2018). "On the other hand, IGJ, IGLJ3, and IGLC1 were found to be either characteristic or prognostic of a number of solid and hematologic malignancies." (PMID 29483918, 2018).
IGLJ3 also shares sentences with these, for which no sentence is quoted: chronic myeloid leukemia (1 paper); intrahepatic cholangiocarcinoma (1); tumor (1); type 1 diabetes (1).